UBE2Q1 (ubiquitin conjugating enzyme E2 Q1)
Description:
Catalyzes the covalent attachment of ubiquitin to other proteins. May be involved in hormonal homeostasis in females. Involved in regulation of B4GALT1 cell surface expression, B4GALT1-mediated cell adhesion to laminin and embryoid body formation (By similarity).
Synonyms: NICE5; UBE2Q; PRO3094; NICE-5; GTAP
Tractability: PROTAC: UniProt records ubiquitination sites on it; ubiquitination databases record sites on it; its protein half-life has been measured.
Gene: Protein-coding gene on chromosome 1 (154,548,550 to 154,559,028, reverse strand). Ensembl gene ENSG00000160714.
Subcellular location: Nucleus; Cell projection, filopodium; Cytoplasm, cytosol
Subcellular location (Human Protein Atlas): Nucleoplasm; Centrosome; Cytosol
Pathways (Reactome):
Immune System: Antigen processing: Ubiquitination & Proteasome degradation
Gene Ontology:
Molecular function: protein binding; ubiquitin conjugating enzyme activity; ubiquitin-protein transferase activity
Biological process: protein polyubiquitination; protein ubiquitination
Cellular component: nucleus; cytosol; filopodium
Genetic constraint (gnomAD): Loss-of-function variants: 6 observed, 56.15 expected, observed/expected ratio (o/e) 0.11, 90% interval 0.058 to 0.21. The upper end of that interval is the gene's LOEUF score, 0.21, which puts it in group 1 of 6, group 1 being the genes least tolerant of losing a copy. Missense variants: 259 observed, 501.43 expected, observed/expected ratio (o/e) 0.52, 90% interval 0.47 to 0.57. Synonymous variants: 221 observed, 192.7 expected, observed/expected ratio (o/e) 1.15, 90% interval 1.03 to 1.28.
Homologues: Orthologues: chimpanzee UBE2Q1 (100% identical), dog UBE2Q1 (99% identical), guinea pig UBE2Q1 (99% identical), pig UBE2Q1 (99% identical), mouse Ube2q1 (99% identical), rat Ube2q1 (99% identical), macaque UBE2Q1 (98% identical), rabbit UBE2Q1 (55% identical). Paralogues in human: UBE2Q2 (67% identical), UBE2QL1 (22% identical), UBE2E3 (15% identical), UBE2E2 (14% identical), UBE2E1 (13% identical), UBE2D4 (11% identical), UBE2D1 (11% identical), UBE2D2 (11% identical), UBE2D3 (11% identical), UBE2L5 (8% identical), UBE2L3 (8% identical), UBE2L6 (7% identical).
Diseases named in the same sentence as UBE2Q1 in open-access papers:
UBE2Q1 is named in the same sentence as 20 diseases in open-access papers, as found by Europe PMC text mining. Sharing a sentence is not in itself a finding about the gene and the disease. The quoted sentences say what the papers report.
hepatocellular carcinoma (6 papers, 2019 to 2022). A malignant tumor that arises from hepatocytes. "In a previous study, UBE2Q1 has found to stabilize β-catenin in hepatocellular carcinoma, and β-catenin interacts with HIF-1α under hypoxic conditions." (PMID 35156520, 2022). "UBE2Q1 is a specific E2 ubiquitin-conjugating enzyme, which acts as an oncogene in hepatocellular carcinoma." (PMID 34163524, 2021). "UBE2Q1 has been identified as a poor prognosticator for hepatocellular carcinoma and early stage laryngeal cancers." (PMID 33663405, 2021). "Expectedly, the prognosticators of early stage laryngopharyngeal cohort were completely unique and included TWISTNB and UBE2Q1, previously designated poor prognosticators in breast and hepatocellular cancers." (PMID 31310629, 2019). "UBE2Q1 is a potential biomarker for hepatocellular carcinoma and ovarian cancer, and may also function in female hormone homeostasis (for example,)." (PMID 34768809, 2021). "Higher UBE2Q1 levels have been detected in hepatocellular carcinoma (HCC) tumors compared to adjacent normal tissues." (PMID 33805973, 2021). "Ubiquitin-conjugating enzyme E2Q family member 1 (UBE2Q1), a target gene of miR-338-3p, has been found to stabilize β-catenin in hepatocellular carcinoma." (PMID 35156520, 2022). "Although increased expression of UBE2Q1 has been observed in various cancers such as breast cancer, colorectal cancer and hepatocellular carcinoma, no previous report has explored this gene in ovarian cancer to best of our knowledge." (PMID 33663405, 2021). "Based on these findings, a potential miR-497-mRNA or miR-1246-mRNA regulatory network can be established, namely, miR-497-ARL2/UBE2Q1/PHF19/APLN/CHEK1/CASK/SUCO/CCNE1/KIF23, or miR-1246-AUTS2/SLAIN1, which contributes to the occurrence and development of hepatocellular carcinoma." (PMID 34163524, 2021). "Another study analysed promoter methylation of UBE2Q1 in serum of hepatocellular carcinoma (HCC) patients and demonstrated low levels of UBE2Q1 DNA methylation as a potential biomarker for hepatitis B-virus (HBV) positive HCC." (PMID 33663405, 2021).
breast carcinoma (3 papers, 2021 to 2022). "We, for the first time identify UBE2Q1 as a potential prognostic marker for aggressive ovarian and breast cancers and predictive marker for platin/taxane chemotherapy in high grade serous ovarian carcinoma." (PMID 33663405, 2021). "Further, both in ovarian and ER−/HER2- breast cancer patients, a co-expression pattern for UBE2Q1 alongwith B4GALT3 was observed suggesting a functional interaction and potential pathological contribution of these two genes in the cancer subtypes." (PMID 33663405, 2021). "Considering etiological similarities in ovarian and breast cancer, we compared expression of UBE2Q1 in different breast cancer subtypes and observed highest expression in most aggressive basal-like breast cancer patients, which are essentially negative for HER2 and estrogen receptors." (PMID 33663405, 2021). "Hence, we investigated the expression of UBE2Q1 in different subtypes of breast cancer categorised based on 3-Gene classifiers subtypes i.e. Basal like, Her2-enriched, Luminal A, Luminal B and normal-like." (PMID 33663405, 2021). "We have observed differential overexpression of B4GALT3 and also a co-expressional pattern with UBE2Q1, however it does not correlate with ovarian and breast cancer prognosis." (PMID 33663405, 2021).
colorectal cancer (3 papers, 2014 to 2022). A primary or metastatic malignant neoplasm that affects the colon or rectum. "Consistently, it was found that UBE2Q1 overexpression increased the expression of β-catenin and also increased the ubiquitination level of β-catenin and elongated its half-life in colorectal cancer cells." (PMID 35156520, 2022). "Herein, it was found that LINC00525 and miR-338-3p reduced the expression of each other by binding, and miR-338-3p overexpression and LINC00525 knockdown inhibited UBE2Q1 protein expression in colorectal cancer cells." (PMID 35156520, 2022). "The goal of this study was to demonstrate that LINC00525 activated HIF-1α through miR-338-3p/UBE2Q1/β-catenin axis to regulate the Warburg effect in colorectal cancer." (PMID 35156520, 2022). "The previous study has found that UBE2Q1 was highly expressed in colorectal cancer, and increased the levels of β-catenin protein by stabilizing β-catenin in cancer cells, and β-catenin interacts with HIF-1α under hypoxic condition." (PMID 35156520, 2022). "In conclusion, these findings showed that LINC00525 was essential for hypoxia-enhanced glycolysis; its mechanism was related to activating HIF-1α through miR-338-3p/UBE2Q1/β-catenin axis in colorectal cancer cells." (PMID 35156520, 2022). "Although this finding is dissimilar to those of our previous studies indicating the up regulation of UBE2Q1 in breast and colorectal carcinomas, however, this may suggest a different way of involvement of this gene in ALL development." (PMID 25035859, 2014). "In this study, it was hypothesized that LINC00525 regulated the expression of UBE2Q1 is activated by miR-338-3p via the bridging effect, whereas UBE2Q1 activated HIF-1 via stabilizing-catenin, ultimately promoting hypoxia-enhanced glycolysis in colorectal cancer." (PMID 35156520, 2022).
frontotemporal dementia (3 papers, 2024 to 2025). Frontotemporal dementia (FTD) comprises a group of neurodegenerative disorders, characterized by progressive changes in behavior, executive dysfunction and language impairment, as a result of degeneration of the medial prefrontal and frontoinsular cortices. "The high expression of UBE2Q1 in the brain correlates with its reported role in traumatic brain injury and frontotemporal dementia." (PMID 38536929, 2024). "Other UBE2 enzymes, such as UBE2I, UBE2Q1, UBE2E1, and UBE2Z, display varied regulatory patterns in neurodegenerative diseases like frontotemporal dementia, suggesting the Ube2 family’s extensive influence on neurodegeneration, inflammation, and cellular stress responses." (PMID 39108475, 2024).
acute lymphoblastic leukemia (2 papers, 2014 to 2021). Leukemia with an acute onset, characterized by the presence of lymphoblasts in the bone marrow and the peripheral blood. "Ubiquitin-conjugating enzyme E2 Q1 (UBE2Q1) dysregulation has been observed in several cancers including acute lymphocytic leukemia (ALL), breast, hepatocellular, and colorectal." (PMID 33805973, 2021).
cervical cancer (2 papers, 2020 to 2021). A primary or metastatic malignant neoplasm involving the cervix. "circOSBPL10 absorbed miR-1179, upregulated UBE2Q1 expression, and thus affected cervical cancer cell functions." (PMID 33413360, 2021).
laryngeal carcinoma (2 papers, 2019 to 2021). Carcinoma that arises from the laryngeal epithelium. "Assessment of these genes in clinical sub-cohorts of TCGA indicated that early stage tongue (MTFR1, C8ORF33, OTUD6B) and laryngeal cancers (TWISTNB, KLHL13 and UBE2Q1) were defined by distinct prognosticators." (PMID 31310629, 2019).
ovarian carcinoma (2 papers, 2021). A malignant neoplasm originating from the surface ovarian epithelium. "Our study identifies a potential UBE2Q1 – B4GALT3 functional axis in ovarian cancer, where only the E2 conjugating enzyme showed a poor prognostic impact on the disease." (PMID 33663405, 2021). "Overlapping the most relevant DEG cluster 4 with prominent WGCNA cyan module identified strongest correlation of UBE2Q1 with ovarian cancer and its prognostic significance on survival probability of ovarian cancer patients was investigated." (PMID 33663405, 2021). "To conclude, we find UBE2Q1 as a potential prognostic marker for ovarian cancer patients’ post-chemotherapy with platin/taxane drugs." (PMID 33663405, 2021). "The role of UBE2Q1 in embryo implantation and hormonal homeostasis in females makes this discovery intriguing and further studies will unravel how UBE2Q1 connects hormonal homeostasis with ovarian cancer." (PMID 33663405, 2021). "This is in line with our observation that even in Ovarian cancer, it is the aggressive serous subtype which shows poor prognosis in correlation with high UBE2Q1 expression." (PMID 33663405, 2021). "In this study, we have identified UBE2Q1 as a potential prognostic marker for ovarian cancer." (PMID 33663405, 2021). "The predictive value of UBE2Q1 as a potential biomarker was analysed by correlating its expression with 12-months relapse free survival of patients in response to platin/taxane, the standard first-line chemotherapy for ovarian cancer, and analysing area under the ROC curve." (PMID 33663405, 2021). "To investigate the potential of UBE2Q1 and B4GALT3 as prognostic markers, we performed survival analysis on these genes to identify their effects on relapse free survival of ovarian cancer patients." (PMID 33663405, 2021). "We also propose, a UBE2Q1 – B4GALT3 axis, co-relative overexpression of which is envisaged to have an oncogenic potential in ovarian cancer development." (PMID 33663405, 2021). "To corroborate this finding at cellular level, we analysed UBE2Q1 protein expression in high grade serous ovarian cancer cells (OVCAR8) in comparison to non-high grade ovarian cancer cells (A2780)." (PMID 33663405, 2021). "Thus, our study identifies a potential UBE2Q1 – B4GALT3 functional axis in breast and ovarian cancer, where only the E2 conjugating enzyme showed a poor prognostic impact on the disease." (PMID 33663405, 2021). "UBE2Q1 and UBE2C share their molecular function as ubiquitin conjugating enzyme activity with role in protein turnover, which is altered in many cancers but not yet implicated in ovarian cancer." (PMID 33663405, 2021).
serous ovarian cancer (2 papers, 2021 to 2022). "An integrated gene expression analysis and WGCNA, identified UBE2Q1 as a potential prognostic marker associated with poor relapse-free survival and response outcome to platin/taxane treatment of patients with high grade serous ovarian cancer." (PMID 33663405, 2021). "An AUC value of 0.654 (p value = 1.2e-04) suggests a convincing potential of UBE2Q1 as a predictive biomarker of clinical utility to predict relapse free survival of serous ovarian cancer patients of later stages/grades in response to platin/taxane therapy." (PMID 33663405, 2021). "We further analysed the expression of UBE2Q1 gene in experimental GEO dataset GSE66957 which indeed showed significant upregulation of UBE2Q1 in high grade serous ovarian cancer patients in comparison to normal ovarian surface epithelium." (PMID 33663405, 2021). "By performing genome wide expression analysis of tumor samples of high grade serous ovarian cancer patients and generating co-expression patterns of differentially expressed genes (DEGs), we found UBE2Q1 - B4GALT3 axis as an important player in female reproductive cancers." (PMID 33663405, 2021). "Further we validated this result in another dataset GSE10971 termed as ‘validation dataset’ and also found increased expression of UBE2Q1 in tumor samples of high grade serous ovarian cancer patients (n = 11) compared to non-malignant fallopian tube epithelium tissues (n = 24)." (PMID 33663405, 2021).
colon cancers (1 paper, 2014). "In our previous studies we showed that UBE2Q1 is up regulated at mRNA level in head and neck squamous cell carcinoma (unpublished data), and at both protein and mRNA levels in breast and colon cancers." (PMID 25035859, 2014). "Our preliminary study has shown that the newly characterized human gene, UBE2Q1, is differentially expressed in head and neck squamous cell carcinoma (data not published), breast tumor and colon cancer." (PMID 25035859, 2014).
female reproductive cancers (1 paper, 2021). "Thus, we propose a potential role of UBE2Q1 in hormonal homeostasis and a deeper understanding of this function in female reproductive system might give better clues on how UBE2Q1 contributes to female reproductive cancers." (PMID 33663405, 2021).
injury (1 paper, 2015). Damage inflicted on the body as the direct or indirect result of an external force, with or without disruption of structural continuity. "Moreover, the expression levels of UBE2Q1 were found down regulated in rat brain following traumatic brain injury." (PMID 25580532, 2015).
Parkinson disease (1 paper, 2017). A progressive degenerative disorder of the central nervous system characterized by loss of dopamine producing neurons in the substantia nigra and the presence of Lewy bodies in the substantia nigra and locus coeruleus. "On the other hand the decreased expression of ATPase and ubiquitin genes (ATP6AP2, UBE2e1, and Ube2q1) prevent mitochondrial oxidative stress leading to Parkinson's disease, Alzheimer's and X-linked mental retardation." (PMID 28423529, 2017).
prostate carcinoma (1 paper, 2016). A carcinoma that arises from epithelial cells of the prostate gland. "For example, the last four exons of UBE2Q1 and last five exons of RFX6 contributed to increased expression levels in prostate cancer tissues." (PMID 26979803, 2016).
tumor (4 papers, 2020 to 2023). "Previously, UBE2Q1 has been depicted as a critical participator in tumor progression." (PMID 32831649, 2020).
cancer (3 papers, 2021 to 2022). A tumor composed of atypical neoplastic, often pleomorphic cells that invade other tissues. "UBE2Q1 may regulate various protein substrates by ubiquitination and functionally may lead to instability of tumor suppressor genes in cancers." (PMID 33663405, 2021).
UBE2Q1 also shares sentences with these, for which no sentence is quoted: neurodegenerative disease (2 papers); head and neck squamous cell carcinoma (1); influenza (1); melanoma (1).